AIM2 (absent in melanoma 2)
Diseases named in the same sentence as AIM2 in open-access papers (continued):
Sharing a sentence is not in itself a finding about the gene and the disease.
periodontitis (continued). "First, while previous studies detected the activation of AIM2 inflammasome in the pathogenesis of periodontitis and pulpitis, the molecular mechanism by which oral pathogens activate AIM2 has not yet been fully elucidated." (PMID 32903550, 2020). "Interestingly, when researchers looked at gingival tissues rather than saliva, they found higher expression of caspase-1, NLRP3, ASC and AIM2 in patients with chronic periodontitis." (PMID 41440367, 2025). "As we have observed in THP-1 derived macrophages, it is well established that NLRP3 and AIM2 are upregulated in saliva, periapical lesions and gingival tissues of periodontitis patients, driving an increase in IL-1β secretion." (PMID 40490723, 2025). "On the other hand, in NLRP3-KO macrophages, the absence of the feedback loop reduces ROS levels and, although they maintain the ability to induce mtDNA release and activate AIM2, IL-1β secretion and pyroptosis are significantly decreased in both periodontitis and peri-implantitis scenarios." (PMID 40490723, 2025). "The AIM2 inflammasome activation promoted the development of periodontitis." (PMID 39600708, 2024). "In addition to NLRP3 and AIM2, the effects of other canonical inflammasomes on the pathogenesis and development of periodontitis have also been investigated." (PMID 34177950, 2021). "Polymorphisms in various inflammasome components, including NLRP3, AIM2, and IFI16, may be associated with susceptibility to periodontitis." (PMID 34177950, 2021). "In addition, gingival tissues derived from ligature‐induced periodontitis shows a significant two‐fold increase in AIM2 and IFI204 expression compared with controls." (PMID 31850638, 2020). "However, NLRP3, NLRP6, NLRP12, and AIM2 were expressed much higher in gingival tissues with periodontitis than in healthy group, especially for NLRP3 and NLRP12." (PMID 32903638, 2020). "Furthermore, the expression of the AIM2 inflammasome (that recognizes double-stranded DNA) was also more highly expressed in the gingival tissue of periodontitis patients than in controls, as well as in human macrophages infected with P. gingivalis." (PMID 31341421, 2019). "Therefore, the presence of these abnormal genetic variations in AIM2 was linked to a higher likelihood of developing periodontitis, both with and without coronary heart disease." (PMID 41194911, 2024). "Furthermore, a cross-sectional study suggests that the absent in melanoma 2 (AIM2) inflammasome is associated with alveolar bone loss in patients with periodontitis." (PMID 39769377, 2024). "Therefore, whether NLRP3 or AIM2 inflammasomes are more predominant in A. actinomycetemcomitans-induced periodontitis remains unclear." (PMID 34177950, 2021). "Upregulation of inflammasome components caspase-1, NLRP3, and absent in melanoma 2 (AIM2) in gingival epithelial cells and macrophages of periodontitis patients suggests its role." (PMID 35967399, 2022). "Additionally, migrating neutrophils expressing IFI16 and AIM2 were observed in the epithelial layer in gingival tissues derived from individuals with periodontal disease, further supporting a potential role of these proteins in the pathogenesis of periodontitis." (PMID 32533779, 2020). "We recently found that the levels of IL-1β and inflammasome components increased in periodontitis patients and P. gingivalis induced IL-1β release via TLR2/TLR4-NLRP3/AIM2 inflammasome-caspase-1 pathway activation." (PMID 27386246, 2016). "Search terms included combinations of “inflammasome,” “NLRP3,” “AIM2,” “IFI16,” “dental pulp,” “pulpitis,” “periodontitis,” “chronic oral inflammation,” “interleukin-1β,” “interleukin-18,” “oral squamous cell carcinoma,” “oral cancer,” “NF-κB,” “bacterial pathogens,” and related terms." (PMID 41440367, 2025). "In the case of AIM2, there are no studies that have examined in vitro its activation in macrophages within the context of periodontitis or peri-implantitis." (PMID 40490723, 2025).
periodontitis (continued). "Patients with severe periodontitis exhibit significant increases in the expression of interleukin-1β (IL-1β), tumor necrosis factor-α (TNF-α), nod-like receptor protein 3 (NLRP3), and their absence in melanoma 2 (AIM2) inflammasomes in the gingival tissues." (PMID 38921772, 2024). "NLRP3 (Nod-like receptor pyrin domain-containing protein 3) and AIM-2 (Absent in melanoma 2) inflammasomes are associated to periodontal disease, and high levels of their receptors, NRLP3 and AIM-2, are detected in gingival tissues of periodontitis patients." (PMID 34630089, 2021). "Porphyromonas gingivalis is considered a major etiologic agent of periodontitis and activates the NLR family pyrin domain containing 3 (NLRP3) but is absent in melanoma 2 (AIM2) inflammasomes, resulting in pro-inflammatory cytokine release." (PMID 38921772, 2024). "Furthermore, various studies demonstrated increases in the expression of NLRP3, AIM2, IL-1β, and IL-18, but not ASC or NLRP2, in gingival tissue from periodontitis patients when compared to healthy individuals." (PMID 31341421, 2019).
Sepsis (19 papers, 2020 to 2026). Sepsis is defined as life-threatening organ dysfunction caused by a dysregulated host response to infection. "According to the ROC curves, four out of six genes (GZMB, CHMP7, NLRP1, and AIM2) had good diagnostic value in the diagnosis of sepsis, with AUC > 0.9 in both the GSE65682 and GSE95233 datasets." (PMID 36618365, 2022). "Four out of six genes (GZMB, CHMP7, NLRP1, and AIM2) also have potential diagnostic value in sepsis diagnosis." (PMID 36618365, 2022). "Experimental models demonstrate that silencing AIM2 or its downstream effectors significantly reduces IL-1β levels and mitigates tissue damage, highlighting its potential as a therapeutic target in sepsis." (PMID 40558557, 2025). "This review builds upon prior work highlighting NLRP3 as a master regulator of inflammatory signaling in sepsis, while extending current understanding by addressing lesser-explored sensors like AIM2 and IFI16." (PMID 40558557, 2025). "In sepsis-associated AKI, renal AIM2 expression is markedly upregulated, accompanied by GSDMD cleavage (pyroptosis), caspase-3 activation (apoptosis), and p-MLKL accumulation (necroptosis)." (PMID 41583472, 2025). "Previous publications have found a significantly lower expression of NLRP1 and a significantly higher expression of AIM2 among sepsis patients, besides, an even lower expression of NLRP1 was found in the non-survivor." (PMID 36618365, 2022). "The itaconate-AIM2 alkylation axis provides crucial mechanistic insights into macrophage depletion and systemic inflammation, highlighting a potential therapeutic target for severe sepsis." (PMID 42120931, 2026). "Then, we developed a prognostic risk score with six pyroptosis-related genes, including GZMB, CHMP7, NLRP1, MYD88, ELANE, and AIM2, and found that it could predict the prognosis of sepsis patients." (PMID 36618365, 2022). "However, in the context of sepsis—characterized by dysregulated systemic inflammation—persistent microbial or mtDNA may aberrantly activate AIM2, leading to uncontrolled cytokine production and immune exhaustion." (PMID 40558557, 2025). "However, only a small part of MVPs have relatively large Δβ (|Δβ|> 0.2), and focusing on those with large Δβ, we found that 6 of 26 differentially methylated genes (23.1%) were previously associated with sepsis in the literature, including ALK, ZEB2, MNDA, AIM2, TLR5, and JUNB." (PMID 35242787, 2022). "In sepsis-induced acute kidney injury (AKI), AIM2 expression is significantly upregulated and targeted for activation by the EIF2AK2 protein, thereby driving PANoptosis in renal tubular epithelial cells." (PMID 41583472, 2025). "In both datasets, the expression level of AIM2, ELANE, and MYD88 were significantly higher in sepsis patients compared to healthy individuals, while the expression level of CHMP7, GZMB, and NLRP1 were significantly lower." (PMID 36618365, 2022). "Our results showed the expression of AIM2, CASP4, NLRC4, and PYCARD was higher and the expression of PVJK and PLCG1 was lower in both sepsis and septic shock patients than in healthy controls." (PMID 36250055, 2022). "Compared to that of healthy individuals, the expression level of AIM2, CASP4, NLRC4, and PYCARD was significantly upregulated, while the expression level of PVJK and PLCG1 was significantly downregulated in both sepsis and septic shock patients." (PMID 36250055, 2022). "In sepsis-induced AKI models, PKM2 inhibition attenuates the activation of NLR family pyrin domain containing 3 (NLRP3) and absent in melanoma 2 (AIM2) inflammasomes, decreases the release of IL-1β, IL-18, and HMGB1 by macrophages, and ultimately improves survival outcomes." (PMID 40843128, 2025). "During sepsis, cfDNA primarily triggers inflammatory responses by activating specific PRR pathways, including TLR9-myeloid differentiation primary response 88 (MyD88), AIM2 inflammasome, and cGAS-STING pathways." (PMID 41327452, 2025).
Sepsis (continued). "AIM2 inflammasome contributed to the release of IL‐1β, IL‐18 and septic death in mice, which was protected by conditional knockout of PKM2, suggesting a novel mechanism of AIM2 regulation by glycolytic metabolism and a potential therapeutic strategy to treat sepsis." (PMID 33682108, 2021). "It activates inflammasomes, such as absent in melanoma 2 (AIM2) and NLRP3, to promote the release of IL-1β and IL-18, enhance pathogen clearance, and modulate inflammation, particularly in sepsis and endotoxemia." (PMID 40788157, 2025). "In sepsis, Toll-like receptor (TLR) 9, absent in melanoma 2 (AIM2), and cyclic GMP-AMP synthase (cGAS) are the principal PRRs responsible for sensing cfDNA." (PMID 41327452, 2025). "The results obtained in other kinds of cytosolic PRRs (e.g., NLRP1, AIM2, or NLRC4) were not representative of the entire pathophysiology encountered in sepsis." (PMID 33679687, 2020).
cervical carcinoma (18 papers, 2019 to 2025). A carcinoma arising from either the exocervical squamous epithelium or the endocervical glandular epithelium. "In HPV-infected cervical cancer cells, AIM2 plays a cancer-suppressive role by promoting pyroptosis." (PMID 35957895, 2022). "In HPV infected cervical cancer cells, aim2 can play a tumor suppressive role by stimulating pyroptosis." (PMID 36199146, 2022). "In HPV infected cervical cancer cells, AIM2 plays a tumor suppressive role by stimulating pyroptosis." (PMID 36199146, 2022). "A study using sirtuin 1 (SIRT1) knockdown showed that SIRT1 has been shown to induce metabolic reprogramming by increasing mitochondrial respiration and repress the NF‐κB‐driven transcription of AIM2, contributing to cervical cancer pathology in patients." (PMID 33682108, 2021). "This implies AIM2 inflammasome plays the tumor‐suppressive role in HPV‐infected cervical cancer." (PMID 34014039, 2021). "However, AIM2 expression is inhibited by the deacetylase Sirtuin 1 (SIRT1) through the destabilization of RELB messenger RNA in HPV‐infected cervical cancer, assisting HPV‐infected tumors in escaping antiviral immunity." (PMID 34014039, 2021). "Besides, AIM2 in HIV-infective cervical cancer cells could induce pyroptosis to protect against cancer cells." (PMID 37305457, 2023). "Moreover, knockdown of SIRT1 not only result in pyroptosis of HPV-infected cervical cancer cells, such as SiHa cells, but it also induces pyroptotic cell death of naïve cervical cancer cells by releasing extracellular vesicles carrying AIM2 inflammasome proteins." (PMID 31861809, 2019). "Furthermore, SIRT1 allows HPV-infected cervical cancer cells to maintain growth levels by nullifying absent in melanoma 2 (AIM2) inflammasome-mediated immunity, and silencing SIRT1 causes these cancer cells to undergo pyroptosis regulated by EVs carrying AIM2 inflammasome proteins." (PMID 38216595, 2024). "In cervical cancer cells, SIRT1 can suppress pyroptosis by interfering with the transcription of AIM2." (PMID 35281845, 2022). "Conversely, AIM2 may exhibit distinct functions in HCC and cervical cancer, potentially through unique mechanisms." (PMID 39744568, 2025). "Finally, an interesting interplay between AIM2 and the NAD+-dependent protein deacetylase Sirtuin 1 (SIRT1) has recently emerged in HPV-induced cervical cancer." (PMID 31861809, 2019).
non-small cell lung carcinoma (18 papers, 2019 to 2025). A group of at least three distinct histological types of lung cancer, including non-small cell squamous cell carcinoma, adenocarcinoma, and large cell carcinoma. "In addition, etoposide (VP16) is a commonly used chemotherapeutic drug in non-small cell lung cancer that can cause DNA damage to activate the AIM2 inflammasome." (PMID 31862870, 2019). "Other studies indicate that AIM2 enhances tumor progression in non-small cell lung cancer, lung adenocarcinoma and squamous cell carcinoma." (PMID 41062723, 2025). "In contrast, AIM2 functioned as an oncogene in Non-small-cell lung cancer (NSCLC) in an inflammasome-dependent way." (PMID 36386141, 2022). "AIM2 aberrant expression has been reported in several cancer types such as prostate cancer and non-small-cell lung cancer." (PMID 33918195, 2021). "A recent study showed that AIM2 was highly expressed in non-small cell lung cancer (NSCLC) and promoted tumor development in an inflammasome-dependent manner." (PMID 31242947, 2019). "Furthermore, the AIM2 inflammasome enhances non-small cell lung cancer by promoting the entry of cancer cells into the G2/M phase." (PMID 41062723, 2025). "The role of AIM2 may be controversial in different cancer types; in our study, upregulation of AIM2 was associated with shorter OS time in PDAC, consistently with that in nasopharyngeal carcinoma and non-small cell lung cancer." (PMID 36196256, 2022). "AIM2 was overexpressed in non-small cell lung cancer and facilitated cell proliferation." (PMID 35070978, 2021). "AIM2 promotes non-small-cell lung cancer cell growth through an inflammasome-dependent pathway." (PMID 34680930, 2021). "However, AIM2 promotes cell growth in non-small-cell lung cancer." (PMID 33162829, 2020). "Furthermore, AIM2 senses e.g. IR-induced DSBs within 60 min, and a role for AIM2 overexpression in A549 cell proliferation and epithelial mesenchymal transition (EMT) in non-small cell lung cancer was recently suggested." (PMID 32778128, 2020). "In non-small cell lung carcinoma, luteolin induced G2/M cell cycle arrest and reduced EMT by reducing the expression of absent in melanoma 2 (AIM2), leading to decreased AIM2 inflammasome activation which was also seen in lung cancer mouse xenograft models." (PMID 32708138, 2020).
lung cancer (16 papers, 2020 to 2025). A malignant neoplasm involving the lung. "Furthermore, AIM2 has been implicated in the promotion of lung cancer progression by modulating mitochondrial dynamics and other cellular pathways." (PMID 39744568, 2025). "Thus, AIM2 was identified as a novel diagnostic tool to predict lung cancer establishment." (PMID 40002808, 2025). "However, our group demonstrated that AIM2 inflammasome could play a pro-carcinogenic role in lung cancer, in that its activation in tumor-associated pDCs leads to high levels of IL-1α which favors lung tumor cell proliferation in a caspase-4-dependent manner." (PMID 34084280, 2021). "All together, these studies provide insights into the pro-tumor function of AIM2 in lung cancer, paving the way for further studies focusing on therapeutic strategies targeting AIM2 in order to counter lung carcinogenesis progression." (PMID 40002808, 2025). "High expression of AIM2 is observed in some malignancies, e.g., lung cancer, and nasopharyngeal carcinoma; depending on the type of cancer, AIM2 plays a pro-cancer or anti-cancer role." (PMID 36823654, 2023). "Interestingly, reports suggest that AIM2 can activate polarization toward M2 macrophages, contributing to immune escape in lung cancer therapy." (PMID 39222064, 2024). "Activation of the AIM2 inflammasome promotes EMT in lung cancer." (PMID 34014039, 2021). "Furthermore, AIM2 expression is upregulated in oral, cervical, and lung cancer and downregulated in colorectal and small bowel cancer." (PMID 33584697, 2020). "In the following subparagraphs, we reviewed the pro-tumor activity of AIM2, focusing on the recent findings about the involvement of the AIM2 receptor in the establishment and progression of ovarian and prostate cancer, oral malignancies, pancreatic and lung cancer." (PMID 40002808, 2025). "We found that AIM2 inflammasome is at the crossroad between COPD and lung cancer in that its higher presence is correlated to lower survival rate of smoking COPD adenocarcinoma patients." (PMID 34084280, 2021). "Based on this concept, the main goal of this study was to evaluate whether AIM2 was at the crosstalk between smoking-COPD and COPD-induced lung cancer." (PMID 34084280, 2021). "We found that AIM2 expression was not altered in the lung of both smoking mice and in the cancerous tissue of lung cancer patients, independently of COPD and smoking status." (PMID 34084280, 2021).